SPDYE16 (speedy/RINGO cell cycle regulator family member E16)
Tractability: No criterion of Open Targets' tractability assessment is met for any kind of drug.
Gene: Protein-coding gene on chromosome 7 (76,531,313 to 76,543,297, reverse strand). Ensembl gene ENSG00000185040.
Gene Ontology:
Molecular function: protein kinase binding
Genetic constraint (gnomAD): Loss-of-function variants: 4 observed, 12.69 expected, observed/expected ratio (o/e) 0.32, 90% interval 0.15 to 0.72. The synonymous counts are far from expectation, so gnomAD's model fits this gene poorly and the ratio says little. Missense variants: 83 observed, 153.42 expected, observed/expected ratio (o/e) 0.54, 90% interval 0.45 to 0.65. Synonymous variants: 30 observed, 53.51 expected, observed/expected ratio (o/e) 0.56, 90% interval 0.42 to 0.76.
Homologues: Orthologues: mouse Spdye4a (39% identical), rat Spdye4 (39% identical), mouse Spdye4b (34% identical). Paralogues in human: SPDYE18 (98% identical), SPDYE21 (95% identical), SPDYE2 (93% identical), SPDYE2B (93% identical), SPDYE5 (93% identical), SPDYE6 (93% identical), SPDYE1 (92% identical), SPDYE3 (71% identical), SPDYE12 (63% identical), SPDYE13 (63% identical), SPDYE14 (63% identical), SPDYE15 (63% identical), and 6 more.